GAS5 (growth arrest specific 5)
Diseases named in the same sentence as GAS5 in open-access papers (continued):
Sharing a sentence is not in itself a finding about the gene and the disease.
cancer (continued). "As previously discussed, the GAS5/miR-21 axis has been well defined in cancer studies, and unsurprisingly it has also been a significant area of focus in other areas of biomedical research, such as cardiovascular disease." (PMID 39941145, 2025). "Long non-coding RNAs (lncRNAs) such as GAS5 and CASC8 have been implicated in cancer susceptibility." (PMID 40243746, 2025). "They used lab experiments and mouse models to show that reducing GAS5 or SMARCA4 can slow down cancer growth." (PMID 40451925, 2025). "The cancer stages were grouped by using the American Joint Committee on Cancer (AJCC) staging system, and UALCAN analysis was performed using independent t-tests comparing GAS5 expression in each cancer stage to normal tissues and between stages." (PMID 39958058, 2025). "The expression of GAS5 in different types of cancers was determined and then evaluated for its correlation with clinicopathological parameters, immune cell infiltration, survival outcome, and the methylation status of its promoter." (PMID 39958058, 2025). "In general, GAS5 has been demonstrated to play significant roles in the suppression of cancers through the regulation of oncogenic signaling pathways, cell cycle progression, and cellular apoptosis." (PMID 39941145, 2025). "Consistent with our current discoveries regarding overexpression in these cancer types, prior research has demonstrated that GAS5 functions as an oncogene when expressed in specific conditions or contexts." (PMID 39958058, 2025). "Among the highly expressed lncRNAs are GAS5 (also known as SNHG2), SNHG1, NORAD, and NEAT1, abundant transcripts implicated in cell-cycle control, cancer progression, DDR, and inflammation, respectively." (PMID 41369348, 2025). "According to our analysis, GAS5 was significantly upregulated in these cancers compared to normal tissues." (PMID 39958058, 2025). "We analyzed the expression levels of GAS5 mainly in LIHC because of the availability of radiation therapy data from the TCGA Pan-Cancer Atlas dataset accessed via cBioPortal." (PMID 39958058, 2025). "In cancer, GAS5 functions through mechanisms such as c-Myc translation repression, YBX1/p21 pathway regulation, and EZH2 suppression, providing cellular protection in each context." (PMID 39941145, 2025). "The overexpressed GAS5 has increased G2/M cell cycle arrest with unrepaired DNA damage and thus makes cancer cells more sensitive to ionizing radiation." (PMID 39958058, 2025). "This highlights the broad therapeutic potential of targeting the GAS5/miRNA axis to modulate cancer progression and improve treatment outcomes." (PMID 39941145, 2025). "While GAS5 upregulation demonstrates clear therapeutic potential in cancer, its effects in cardiovascular and inflammatory diseases rely heavily on the target cell type and context of the disease, allowing it to have either detrimental or protective functions." (PMID 39941145, 2025). "This study focuses on a molecule GAS5, which is typically low in many cancers but found at elevated levels in HCC." (PMID 40451925, 2025). "Due to its inverse correlation with miR-21, GAS5 repression has been characterized as a biomarker in various cancers." (PMID 39941145, 2025). "These sequence differences can alter the thermodynamic properties of the RNA, including folding enthalpy and entropy, which together determine secondary structure stability, influencing GAS5's regulatory capacity in cancer-related pathways." (PMID 40521240, 2025). "Based on these studies, it is believed that the suppression of miR-21 and upregulation of GAS5 have therapeutic potential for the treatment of cancer diseases." (PMID 39941145, 2025). "Numerous long noncoding RNAs have been reported to exhibit aberrant expression in cancer, with some, such as GAS5 and HOTAIR, emerging as prominent examples." (PMID 40903777, 2025). "In KIRC patients, GAS5 expression was significantly upregulated in all cancer stages versus normal samples (p < 0.0001)." (PMID 39958058, 2025).
cancer (continued). "Our results showed significant overexpression of GAS5 in 9 out of 17 cancers (GENT2) and 12 out of 34 cancers (TCGA) compared with corresponding noncancerous tissues." (PMID 40451925, 2025). "Lastly, GAS5 displays unique RNA–protein interactions in viral pathogenesis, such as acting as a decoy for viral NS3 or regulating YBX1 in HBV-associated cancers." (PMID 39941145, 2025). "This pan-cancer analysis identified GAS5 as a multifunctional lncRNA with deep implications in cancer biology." (PMID 39958058, 2025). "GAS5 is a regulator of cell proliferation and apoptosis and known to have reduced expression in a variety of human cancers, including several B-cell cancers." (PMID 40452889, 2025). "Future studies on GAS5 should focus on confirming its role in cancer by using laboratory studies, including in vitro and in vivo experiments." (PMID 39958058, 2025). "Initially noted for its involvement in regulating cancer cells cycle arrest and programmed cell death, the lncRNA GAS5 has been suggested to function as a competitive microRNA sponge or protein interaction partner." (PMID 40563948, 2025). "Recent advances in the understanding of the role played by GAS5 in cancer have shown tremendous therapeutic potential, especially in overcoming resistance to therapy and increasing treatment efficacy." (PMID 39958058, 2025). "Previous studies have demonstrated that GAS5 acted as a sponge for miR-21, influencing the proliferation and migration of cancer cells." (PMID 37672149, 2024). "GAS5 is negatively regulated by the m6A reader YTHDF3: m6A modification sites on lincRNA-GAS5 are recognized by YTHDF3, leading to GAS5 degradation and promoting cancer progression." (PMID 39280246, 2024). "On the other hand, some lncRNAs were found to have a role in the inhibition of cancer cells proliferation and activation of apoptosis such as GAS5 which act by triggering CHOP and caspase-9 signal pathways." (PMID 39609501, 2024). "Another study found that MEG3, GAS5, and several miRNAs influence NK cell killing effectiveness in various cancer types." (PMID 39257589, 2024). "LncRNA GAS5, which is lowly expressed in most cancers, can suppress the expression of many oncogenes, and also activate the expression of other tumor suppressor genes." (PMID 38782769, 2024). "It should be also noted that the suppressor and regulatory functions of GAS5 via miRNA in cancer were widely demonstrated, in particular in OC reports concerning five different miRNAs, for example, miR-21 and miR-23a." (PMID 39519394, 2024). "In breast and other cancer cell lines, GAS5 plays an important role in affecting cell growth and determining apoptosis." (PMID 37444428, 2023). "Previous studies have reported that GAS5 can contribute to the resistance function in various types of cancers, including gastric cancer, lung cancer, renal cancer, and hepatocellular carcinoma." (PMID 37198993, 2023). "YTHDF3 regulates YAP signaling by facilitating m6A-modified lncRNA GAS5 degradation and mediates cancer progression." (PMID 37537521, 2023). "The circulating levels of GAS5 in patients with solid cancers can be modulated in response to different anti-cancer therapies, including chemotherapy and TKI." (PMID 37444428, 2023). "As in other cancers, GAS5 can interact with different miRNAs and thus weaken the effect of miRNAs on mRNA targets." (PMID 37444428, 2023). "In NSCLC and HCC, low levels of GAS5 were found in plasma from cancer patients compared with healthy controls." (PMID 37444428, 2023). "The lncRNAs transcript-1 PCAT1 and growth arrest-specific 5 (GAS5) play important roles in stimulating cancer cell proliferation and apoptosis by modulating the Wnt/β-catenin signaling pathway." (PMID 37373000, 2023). "GAS5 is downregulated in many cancers including breast, prostate, lung and colorectal cancer, and its reduced expression correlates with poor prognosis." (PMID 37407839, 2023).
cancer (continued). "Taken together, these data suggest that GAS5 is able to modulate the action of anti-cancer treatments in a selective way, likely due to the mechanisms of action of the different drugs." (PMID 37444428, 2023). "While GAS5 is downregulated in numerous cancers, including osteosarcoma, the role that GADD45b plays in cancer is less clear, as there are reports of decreased expression of GADD45b in some cancers and increased expression in other cancers." (PMID 37349371, 2023). "In a non-cancer setting, GAS5 participates in diabetic wound healing promoted by topical mevastatin." (PMID 37407839, 2023). "The lncRNA Growth arrest-specific transcript 5 (GAS5) has gained much attention in recent research because of its anti-cancer effect." (PMID 37198993, 2023). "Our results demonstrate the role of GAS5 as a ceRNA of miR-128-3p in 5-FU resistance by promoting BAX-inducing cell death and suggest a potential use of GAS5 for effective chemotherapy to improve the efficacy of anti-cancer drugs." (PMID 36672566, 2022). "The comet assay showed that more DNA damage remained unrepaired in the GAS5 group, indicating a role of GAS5 in cancer radiosensitization." (PMID 35059460, 2022). "Silencing of GAS5 decreased cancer cell viability and reduced autophagy via regulating miR-23a expression." (PMID 36685879, 2022). "The biological function of GAS5 was complex, and it depends on the type of cancers and the targets in the downstream." (PMID 36062165, 2022). "The value of GAS5 as a molecular marker in the prevention and treatment of cancers is also discussed." (PMID 35837102, 2022). "lncRNA GAS5 is a well-established tumour suppressor that has been vastly covered in cancer research." (PMID 36671717, 2022). "Dysregulation of GAS5 is involved in the pathophysiological process of diseases, including various types of cancer, neurological disorders, and bone diseases." (PMID 36672566, 2022). "This article reviews the recent discoveries on GAS5, including its expression levels in different tumors, its biological behavior, and its molecular regulation mechanism in human cancers." (PMID 35837102, 2022). "The silencing of miR-196a expression would not only inhibit its cancer-promoting effect but also increase the levels of GAS5, a potential target for ESCC treatment." (PMID 35241975, 2022). "lncRNA GAS5 has been recognized as a tumor suppressor in several types of cancers, including breast cancer, prostate cancer, lung cancer, and colorectal cancer." (PMID 36497250, 2022). "Here, we demonstrate the role of GAS5 in the regulation of chemoresistance against an anti-cancer drug, 5-FU." (PMID 36672566, 2022). "In this part, we will focus on the latest discoveries and various features of GAS5 that regulate malignant tumors." (PMID 35837102, 2022). "Future studies are required to fully elucidate the mechanism of how resistant cells have a lower level of GAS5, which leads to chemoresistance to anti-cancer drugs." (PMID 36672566, 2022). "GAS5 upregulation inhibits proliferation and promotes apoptosis of pituitary neuroendocrine and liver cancer cells." (PMID 36230902, 2022). "Although the detailed mechanisms of GAS5-mediated regulation of drug response need to be further investigated, these findings suggest a potential strategy for combating anti-cancer drug resistance by targeting GAS5." (PMID 36672566, 2022). "The long noncoding RNA growth arrest-specific transcript 5 (GAS5) has been reported to function as a suppressor in many cancers." (PMID 35435104, 2022). "GAS5 overexpression induces cancer cells to stay in the G0/G1 phase and inhibits the expression of G6PD and NOX4, further leading to a decrease in O2∸." (PMID 35837102, 2022). "We found that overexpression of GAS5 significantly suppressed the proliferation of MCF-7 cancer cells." (PMID 35059460, 2022). "The level of GAS5 decreased in 5-FU resistant cells, and its ectopic expression promoted cell death in response to anti-cancer drugs." (PMID 36672566, 2022).
cancer (continued). "One lncRNA module was confirmed to be associated with cancer metastasis, and nine hub lncRNAs, namely FTX, AC005261.1, NORAD, LINC01578, AC004542.2, ZFAS1, EBLN3P, THUMPD3-AS1, and GAS5, were discovered." (PMID 36514044, 2022). "This adds to the idea that reduced GAS5 expression has the same effect in AML as in other types of cancer." (PMID 35054253, 2021). "One of the first lncRNAs that was shown to play a major role in the pathogenesis of cancer is growth arrest-specific transcript 5 (GAS5)." (PMID 35054253, 2021). "Further research showed that lncRNA GAS5 suppresses cancer proliferation by acting as a molecular sponge for miRNA-21, leading to the de-repression of phosphatase and tension homologs." (PMID 34938660, 2021). "Recently, it has been reported that GAS5 is also involved in the therapy resistance of cancer by modulating the expression of various gene targets." (PMID 34760707, 2021). "Later studies have suggested GAS5 as a tumor suppressor gene in various types of cancer through inhibiting proliferation, invasion and promoting apoptosis." (PMID 34094978, 2021). "Aside from its role in cancer cells, GAS5 also has been shown to have a regulatory function on immune response and on macrophages in the TME." (PMID 34439281, 2021). "A recent lncRNA study that systematically surveyed the pharmacologic role of lncRNAs shows that the expression of GAS5 correlates with the sensitivity of over 100 anti-cancer drugs in a collection of pan-cancer cell lines." (PMID 34094978, 2021). "Some studies showed that GAS5 is correlated with poor prognosis in several cancer types including NSCLC and GC." (PMID 33522932, 2021). "Although the majority of malignancies were suppressed via the higher level of GAS5, certain cancers benefited from the presence of GAS5." (PMID 33925911, 2021). "A decrease in the level of SNORD76 correlates better with cancer stage, according to the World Health Organization’s classification, than a decrease in the expression of the host gene, GAS5." (PMID 34202777, 2021). "The results demonstrated that a higher GAS5 mRNA level was found in the poor-differentiated cancer cells than the moderate-differentiated cancer cells." (PMID 33925911, 2021). "Meanwhile, GAS5 interacts with the pathology of variety cancers by inhibiting cell proliferation, suppressing invasion and metastasis, stimulating apoptosis, as well as the induction of cell cycle arrest." (PMID 34760707, 2021). "MiRNA-21 has been identified as a target of GAS5, with high GAS5 expression correlating with low miRNA-21 levels in cancer cells." (PMID 35464754, 2021). "LncRNA GAS5 (growth-arrest specific transcript 5) is known as a cancer-suppressor that regulates cell growth, survival, and proliferation and is also involved in cancer and T2DM aetiology." (PMID 33920227, 2021). "m6A reader YTHDF3 facilitates the degradation of m6A-modified lncRNA GAS5 and thus contributes to cancer development." (PMID 34771549, 2021). "The Growth Arrest-Specific 5 lncRNA (lncGAS5, GAS5) serves as an antioncogene linked to many cancers and has been isolated from NIH3T3 cells." (PMID 33418541, 2021). "Altered expression of lncRNAs, such as PTENP1, linc-PINT, and GAS5, plays an essential role in regulating apoptosis in cancer cells." (PMID 33805687, 2021). "GAS5 plays an essential role in cycle arrest, apoptosis, and regulation of cancer cell survival and is located on chromosome 1q25.1." (PMID 33805687, 2021). "miR-34a had also been identified as a target of GAS5 in malignant glioma and other cancer types, such as renal cell carcinoma and hepatocellular cell carcinoma." (PMID 33391419, 2021). "A known cell cycle-associated lncRNA is the growth arrest-specific transcript 5 (GAS5), which is found downregulated in several cancers where its overexpression results in cell cycle arrest or apoptosis." (PMID 34556693, 2021). "In CRC, LncRNA GAS5 inhibits the proliferation of cancer cells and promotes apoptosis by targeting miR-222-3p." (PMID 34660700, 2021).
cancer (continued). "The role of GAS5 in cancer ontogenesis and progression is a relatively new subject of investigation." (PMID 33076450, 2020). "The agreement of different studies on the role of GAS5 makes it a new attractive target for the prognosis and therapy of different cancer types." (PMID 33076450, 2020). "Among highly expressed lncRNAs, the growth arrest-specific transcript 5 (GAS5) has been reported to be ubiquitously expressed according to serial analysis of gene expression (SAGE) in cancer as well as normal tissue." (PMID 33142861, 2020). "While there is presently no indication for a broader relevance of this fusion event in cancer, GAS5 has in the meantime been confirmed as a transcript with broad implications in oncogenesis and with prognostic potential for various cancers." (PMID 33329688, 2020). "Here, we review both in vitro and in vivo studies showing that GAS5 contributes to the sensitization of cancer cells to chemotherapy and radiotherapy." (PMID 33076450, 2020). "When phytochemicals were administered in combination with chemotherapeutics, they were found to have an additive effect on the overexpression of GAS5 and the sensitization of cancer cells to chemotherapy." (PMID 33076450, 2020). "Upregulation of GAS5 has also been found to decrease cancer invasion, reverse EMT, and induce DNA damage." (PMID 32354045, 2020). "Several studies indicate an overexpression of lncRNA growth arrest-specific 5 (GAS5) reducing angiogenesis via inhibiting the Wnt/β-catenin signaling axis in cancer cells." (PMID 32992718, 2020). "The lncRNA GAS5/YBX1/p21 axis was proved to be a useful target for developing lncRNA-based treatment for cancer." (PMID 32489713, 2020). "The low expression of GAS5 is closely related to the poor prognosis and chemoresistance of many cancers." (PMID 31750253, 2019). "Growth arrest-specific 5 (GAS5) regulates cell proliferation, apoptosis, and invasion in numerous cancers." (PMID 31847392, 2019). "Numerous studies have demonstrated that lncRNA GAS5 is downregulated in various types of human cancers, including HCC." (PMID 30733959, 2019). "LncRNAs such as HOTAIR, MALAT1, GAS5, PC3, and H19 are aberrantly regulated in various malignant tumors and associated with carcinogenesis, metastasis, and prognosis." (PMID 31141943, 2019). "This study highlighted the capability of sorafenib to modulate the expression of a wide range of ncRNAs and specifically, GAS5 and miR-126-3p were involved in the response to sorafenib of different cancer cell types." (PMID 31235746, 2019). "Among these lncRNAs, growth arrest-specific transcript 5 (GAS5) has recently been discovered to suppress cancer." (PMID 31750253, 2019). "Reduced levels of GAS5 transcripts are reported to be indicative of poor prognosis in several types of cancer." (PMID 31212997, 2019). "Recent studies examined GAS5 expression in a variety of cancers including breast, bladder, ovarian, and cervical carcinomas, with a focus on cell proliferation and apoptosis." (PMID 31533355, 2019). "Second, compared with other studies related to CRC and GAS5 expression, the number of paired cancer and adjacent tissues that we used to detect GAS5 expression differences was 210 pairs." (PMID 30902880, 2019). "Our results suggest potential applicability of GAS5 and miR-34a with other conventional markers for various types of cancer." (PMID 30289954, 2018). "LncRNA GAS5 has gained increasing attention in cancer research owing to its ubiquitously high expression during growth arrest." (PMID 29229673, 2018). "Out of numerous cancer-related LncRNAs, growth arrest-specific 5 (GAS5), whose gene is located at chromosome 1q25.1, plays an essential role in the regulation of cancer cell survival." (PMID 29445179, 2018). "Accumulating evidence demonstrates that the long non-coding RNA Growth Arrest-Specific 5 (Gas5) has practical significance in cancer progression and metastasis." (PMID 29423063, 2018).